FAM184B (family with sequence similarity 184 member B)
Synonyms: KIAA1276
Tractability: PROTAC: ubiquitination databases record sites on it.
Gene: Protein-coding gene on chromosome 4 (17,629,306 to 17,781,621, reverse strand). Ensembl gene ENSG00000047662.
Genetic constraint (gnomAD): Loss-of-function variants: 106 observed, 123.47 expected, observed/expected ratio (o/e) 0.86, 90% interval 0.73 to 1.01. The upper end of that interval is the gene's LOEUF score, 1.01, which puts it in group 4 of 6, group 1 being the genes least tolerant of losing a copy. Missense variants: 1,338 observed, 1,298.1 expected, observed/expected ratio (o/e) 1.03, 90% interval 0.99 to 1.08. Synonymous variants: 544 observed, 513.53 expected, observed/expected ratio (o/e) 1.06, 90% interval 0.99 to 1.14.
Homologues: Orthologues: chimpanzee FAM184B (98% identical), macaque FAM184B (96% identical), dog FAM184B (85% identical), pig FAM184B (83% identical), rabbit FAM184B (80% identical), guinea pig FAM184B (78% identical), rat Fam184b (68% identical), mouse Fam184b (67% identical), tropical clawed frog fam184b (28% identical), zebrafish fam184b (28% identical). Paralogues in human: FAM184A (28% identical).
Diseases named in the same sentence as FAM184B in open-access papers:
FAM184B is named in the same sentence as 4 diseases in open-access papers, as found by Europe PMC text mining. Sharing a sentence is not in itself a finding about the gene and the disease. The quoted sentences say what the papers report.
chronic obstructive pulmonary disease (1 paper, 2023). A chronic and progressive lung disorder characterized by the loss of elasticity of the bronchial tree and the air sacs, destruction of the air sacs wall, thickening of the bronchial wall, and mucous accumulation in the bronchial tree. "Interestingly, the FAM184B gene was found to be downregulated in striated muscle tissue and therefore possibly involved in skeletal muscle dysfunction, which is a frequent extrapulmonary manifestation in chronic obstructive pulmonary disease." (PMID 37509437, 2023).
cancer (1 paper, 2023). A tumor composed of atypical neoplastic, often pleomorphic cells that invade other tissues. "In the present study, we found that FAM184B was differentially hypermethylated in cancer-free subjects in oral rinse samples." (PMID 37509437, 2023). "Furthermore, DMPs of AHRR, ADAMTS2, and FAM184 genes passed the sensitivity analysis for cell composition as follows: For the cancer-free subset, cg04450456 for FAM184B, cg02599361 for ADAMTS2." (PMID 37509437, 2023). "In individuals without cancer and heavy smokers, the FAM184B gene was found with two CpG positions differentially hypermethylated (p = 0.012 after FDR adjustment), in a region of 48 bp with an absolute methylation difference >10% between groups (p = 1.76 × 10−8)." (PMID 37509437, 2023).
FAM184B also shares sentences with these, for which no sentence is quoted: atherosclerosis (1 paper); heart disease (1).